TNF (tumor necrosis factor)
Diseases named in the same sentence as TNF in open-access papers (continued):
Sharing a sentence is not in itself a finding about the gene and the disease.
parasitemia (243 papers, 2006 to 2026). "The observed reduction in parasitemia in Mcpt4-/- mice was associated with an earlier type 1 immune response relative to Mcpt4+/+ mice, with increased plasma IL-12p40 and TNF-α by 4 days PI." (PMID 35154114, 2022). "It has been shown that although malarial infection is associated with high parasitemia which culminate in mortality, this condition is associated with a decrease in serum TNFα level." (PMID 33767260, 2021). "Several TNF-α promoter single nucleotide polymorphisms (SNPs) that control gene expression or TNF production are associated with control of parasitemia levels and with increased anti-P." (PMID 31417551, 2019). "In chronically infected mice, serum TNF concentrations are associated with overall disease severity, including parasitemia and parasite load in the heart tissue." (PMID 28877735, 2017). "Parasitemia was significantly correlated with the following cytokines, in order of strength of association: IL-10, IL-12, TNF-α, IFN-γ, IL-1β, IL-6, IL-5, IL-2, IL-4, and IL-7." (PMID 27418744, 2016). "All of the cytokines were negatively associated with parasitemia, with the exception of IL-10, TNF-α, and IL-6." (PMID 27418744, 2016). "The suppression of the production rather than the blockage of action of the potent inflammatory mediator TNFα is a particular hallmark of anti-TNFα mechanisms associated with microbial and parasitic infections." (PMID 22952450, 2012). "Although corticosteroid therapy (CST) may increase susceptibility to parasitic infection through suppression of immune surveillance, our findings showed elevated TNF-α and MMP-9 levels among patients with synovial parasitosis." (PMID 41410796, 2025). "Parasitemia levels were trending towards ultimate clearance; however, indicating that redundant mechanisms in the immune response are present to provide protection in the loss of TNFα signaling." (PMID 39452729, 2024). "Importantly, VLPs vaccination significantly reduced the levels of pro-inflammatory cytokines IFN-γ and TNF-α, decreased parasitemia in blood, resulting in lower body weight loss and longer survival time compared to control." (PMID 35468726, 2022). "However, high concentrations of TNF are associated with death even after the correction of parasitemia and glucose concentrations by multivariate analysis." (PMID 32576141, 2020). "Plasmablasts from T. cruzi-infected mice secrete IL-17, control parasitemia, and decrease plasma TNF levels in muMT-infected mice, since muMT recipients of IL-17A-deficient B cells had higher parasitemia and high levels of TNF compared to muMT recipients of WT B cells." (PMID 29209313, 2017). "Promoter polymorphisms in TNF have been associated with lower levels of parasitemia." (PMID 25887595, 2015). "The first hint that death receptor–mediated apoptosis of T cells exerts a negative impact in the immune response during parasite disease came from studies revealing augmented T cell responses in Fas, Faslg (FasL), or TNF-deficient mice after parasite infection." (PMID 24551250, 2014). "In addition, this study found that anti-GITR treatment was associated with increased TNF-α production and myocarditis as well as tissue parasitemia." (PMID 23509755, 2013). "However, TNFα blockade has been associated with an increase in susceptibility to bacterial, viral and parasitic infections, including Listeria, Mycobacteria and granulomatous infections." (PMID 20463923, 2010). "It remains to be determined whether other TH1 cytokines such as TNF-α contribute to the splenic control of parasitemia in IP-10 deficient mice as it has been observed in previous investigations using P. berghei ANKA parasites." (PMID 19343215, 2009). "It is known that TNF-α promotes the induction of IL-6 and IL-1β; high levels of these cytokines can cause systemic inflammation and the combination of oxidative stress and inflammatory activation is commonly associated to several degenerative processes triggered by parasitosis." (PMID 28177049, 2017).
parasitemia (continued). "Parasitemia assessment, behavioral analysis, levels of proinflammatory cytokines (TNF‐α and IL‐6) in the hippocampus and prefrontal cortex, and levels of the neurotrophin BDNF in the hippocampus." (PMID 41093288, 2026). "Evidence indicates that innate immune mechanisms involving macrophages, dendritic cells, and natural killer cells are critical for early control of parasitemia through cytokine production, including interferon-gamma and tumor necrosis factor-alpha." (PMID 42307388, 2026). "For example, parasitic infections can impair the development of the fetus by increasing the expression of TNF-α in the placenta." (PMID 40007749, 2025). "Silverman and collaborators demonstrated that pretreating monocytes with L. donovani EVs effectively mimics the parasite infection by inhibiting the production of IL-8 and TNF-α while significantly increasing the production of IL-10 and IFN-γ." (PMID 40362539, 2025). "To confirm that the reduction of parasitemia with TNF-α and Z-VAD-FMK in the presence of RIPK3 and MLKL was due to necroptosis, we assessed host cell survival during infection by measuring cell membrane integrity." (PMID 41055414, 2025). "Inflammation associated changes in TNF, NF-κB, and NO in the were examined in the PFC and HPC of mice infected with Tb to assess the neuroinflammatory response associated with parasitic infection using ELISA." (PMID 40977748, 2025). "Together, these results support a model in which Vγ9Vδ2 T cells are activated through BTN3A1, while IL-12 and TNFα license NK cells to produce IFNγ during parasite infection." (PMID 41452934, 2025). "Intracellular cytokine staining confirmed that Vγ9Vδ2 T cells produced most of this cytokine: parasite infection increased both the frequency of TNFα-positive Vγ9Vδ2 T cells and their iMFI, whereas BTN3A1 inhibition returned both measures to baseline." (PMID 41452934, 2025). "We tested both Type I (RH) and Type II (ME49), and despite their differences in virulence, both Type I and Type II strains of T. gondii showed reduced parasitemia in wild-type BMDMs treated with TNF-α and the pan-caspase inhibitor Z-VAD-FMK." (PMID 41055414, 2025). "Positive disease outcome during Δplp1 parasite infection is also associated with regulated induction of proinflammatory cytokines, including IFN-γ and TNF-α, and an earlier IL-10 regulatory response that is dysregulated during WT infection." (PMID 40166190, 2025). "This was attributed to the activation of the inflammatory cascade induced by parasitic infection, and TNF-α stimulated the production of inflammatory cytokines (IL-3, IL-6, and IL-10)." (PMID 40007749, 2025). "First, parasite infection can trigger the host immune response and elevate the levels of pro-inflammatory cytokines such as IL-6, TNF-α, and IFN-γ." (PMID 41333290, 2025). "Our results demonstrate that Fer-1 intervention significantly enhances the secretion of pro-inflammatory cytokines including IFN-γ, TNF-α, and IL-6, effectively boosting antimalarial immune effects and reducing parasitemia levels." (PMID 41422632, 2025). "This elevation potentially aids in controlling parasitemia, as observed by a subsequent decrease in bloodstream parasites following increased TNF-α levels." (PMID 38521853, 2024). "Parasitemia was negatively correlated with plasma TNF-α, which was also positively correlated with an MCP-1–centered network." (PMID 38780542, 2024). "As TNFα also plays an important role in the activation of innate immune cells, we sought to assess the role for TNFα in controlling and clearing parasitemia." (PMID 39452729, 2024). "During parasitic infection, significant upregulation of IL-1β, TNF-α, and Ig gene were observed in C. punctata liver and kidney samples (except TNF-α was downregulated in kidney)." (PMID 38476164, 2024).
parasitemia (continued). "Participants with high parasitemia had raised TNF‐α (p < .001), IFN‐ɣ (p < .001), IL‐1β (p < .001), IL‐6 (p < .001), GM‐CSF (p < .001), and IL‐10 (p < .001), but reduced IL‐3 (p < .001) and TGF‐β (p < .001) than those with low parasitemia." (PMID 39240033, 2024). "Parasite density was the principal predictor of the cytokine levels, as parasitemia positively associated with IL‐10, GM‐CSF, IL‐6, IL‐1β, IFN‐ɣ, and TNF‐α, but negatively associated with IL‐3 and TGF‐β." (PMID 39240033, 2024). "The three primary proinflammatory cytokines associated with parasite infection—IFN-γ, TNF-α, and IL-6—have been identified." (PMID 38521853, 2024). "Both treatments were able to reduce parasitemia, reduce the amount of cardiac and intestinal cytokines, such as TNF- and IL-6, and increase the animals’ survival." (PMID 39598539, 2024). "Mechanistic studies demonstrated that CD4+ T-cells (but not CD8+ T-cells), and Th1 and Th2 cytokines (interferon gamma and tumor necrosis factor, IL-10) were critical in controlling parasitemia and survival following challenge." (PMID 37962347, 2023). "The authors suggested that the status of trace element serum levels in CL patients probably depends on IL-1 and TNF-alpha cytokines secreted by activated macrophages as part of the response to parasite infection." (PMID 37623999, 2023). "This cytokine is up-regulated by TNF-α and acts in concert with other inflammatory mediators to limit parasitemia load." (PMID 36787308, 2023). "O. vulgare and A. paniculata have anti-inflammatory activity that can inhibit inflammatory mediators caused by bacterial and parasitic infections such as prostaglandins, interleukins (IL), interferons (IFN) and tumor necrosis factor (TNF), etc." (PMID 36505504, 2023). "Mice that were treated with TNF-depleting antibodies had a higher peak parasitemia (20.5% ± 3.51% vs 9.76% ± 2.98%; P = 0.0457, AUC) and ~40% survival compared to mice in the rat Ig control group (~90% survival)." (PMID 37962347, 2023). "In parasitic diseases, DHEA has been shown to promote the immune response in patients infected with Trypanosoma cruzi, decreasing parasitemia and TNF-α levels." (PMID 37628731, 2023). "It is known that leishmanicidal mechanisms, such as NO production from macrophages, are activated by IFNγ-producing CD4+ T cells and are further enhanced by TNFα, promoting resistance against parasite infection." (PMID 36851182, 2023). "Animal studies have shown that parasitic infections increased the levels of pro-inflammatory cytokines (TNF-α, IFN-γ, and IL-6) and induced significant changes in the hemostatic system, suggesting a correlation between inflammation and clotting." (PMID 37063881, 2023). "It has been proved that TNF-α has a significant role in the pathogenesis of parasitic infections affecting the brain such as African trypanosomiasis and cerebral malaria." (PMID 37874393, 2023). "These in turn contribute to the control of parasitemia through TNF and Nitric Oxide production and/or phagocytosis." (PMID 36420267, 2022). "IFN-γ and TNF-α together synergize the killing of infectious agents during bacterial and parasitic diseases." (PMID 35955801, 2022). "HO-1 inhibition prevented most of the alterations provoked by the infection leading to a reduction in parasitemia levels as well as hemozoin accumulation, TNF levels, iron deposition and lipid peroxidation at implantation sites." (PMID 35619717, 2022). "The only cytokine identified, but associated with the B. gibsoni infection, is tumor necrosis factor-alpha (TNF-α), which was found in higher concentrations in dogs with higher peripheral parasitemia and a more severe disease." (PMID 35327127, 2022). "Observed in the initial phase of the infection are typical macrophage activity, driven by IFN-γ elevation and potentiated by TNF-α activity, and elevation in the levels of other cytokines, such as IL-17, in response to parasitemia." (PMID 35371021, 2022).
parasitemia (continued). "For instance, orally T. cruzi infected mice present higher parasitemia, mortality rates, and TNF-α serum levels." (PMID 36439149, 2022). "IFN-γ and TNF cytokines are essential for the control of parasitemia and for the survival of infected animals in the acute phase." (PMID 35138142, 2022). "The moderate classification of parasitemia was associated with increased BUN levels, A/G ratio, urinary potassium, total leukocyte content, and levels of the cytokines TNF-α, IFN-γ, IL-12p40, and IL-17." (PMID 35371021, 2022). "Following infection, macrophages secrete inflammatory mediators such as IL-1β, IL-6, and TNF-α to control parasitemia." (PMID 36713380, 2022). "We assessed the serum levels of six cytokines (i.e. IL-1α, IL-1β, IFNγ, CXCL10, CXCL9, TNFα) at the first peak of parasitemia of both 1/148 and IL3000 infections." (PMID 35787830, 2022). "The only cytokine identified, but associated with B. canis infection, is tumor necrosis factor alpha (TNF α), which was found in higher concentrations in dogs with higher peripheral parasitemia and more severe disease." (PMID 35327136, 2022). "Spearman analysis revealed an early (day 4 PI) correlation of Mcpt4-/- parasitemia with TNF-α and IFN-γ, inflammatory cytokines known for their roles in pathogen clearance, a pattern that was observed in Mcpt4+/+ mice much later (day 10 PI)." (PMID 35154114, 2022). "TNFα is involved in the inflammatory response to bacterial, viral, and parasitic infections by activating macrophages to produce carbonic oxide to suppress the mitochondria productivity, causing the parasites to die from energy drain." (PMID 34828435, 2021). "In this context, also TNF has been described as a cytokine involved in the peak parasitemia control of T. b." (PMID 34200074, 2021). "Animal studies have found higher parasitemia and mortality among protein-restricted diet feed mice and impaired inflammatory immune response (lower macrophage activation of TNF-a, IL-10, and NO)." (PMID 34067079, 2021). "Upon parasite infection, levels of pro- and anti-inflammatory cytokines TNF-α, IFN-γ, IL-10, and IL-4 were increased by 7.0, 10.0, 14.0, and 1.5 times, respectively, in the systemic blood circulation of infected mice." (PMID 33803419, 2021). "TNFα and IL-1β are proinflammatory cytokines crucial for immune responses, especially important for host defense from bacterial, viral, and parasitic infections." (PMID 33776573, 2021). "While some cytokines reached a maximum at peak parasitemia (IL-8, IL-10, KC-like) others rose only after the infection was treated (TNF, IL-6, MCP-1)." (PMID 34399690, 2021). "Group A showed a high degree of parasitemia, TNFα expression, low fetal weight, and high cytoadhesion in the placenta." (PMID 34822508, 2021). "They investigated the effects of the seaweed extract of Eucheuma cottonii in combination with DHP (dihydroartemisinin-piperaquine) on the degree of parasitemia, cytoadhesion, TNFα level and fetal development in mice infected with P. berghei." (PMID 34822508, 2021). "CD16+ DCs isolated at peak parasitemia also had increased functionality during in vitro restimulation with iRBCs, with increased TNF production by both TNF-only and TNF/IL-10 producing CD16+ DCs." (PMID 31900030, 2020). "Results available so far show that the combination of anti-trypanosome antibodies and an inflammatory immune environment, in particular the presence of TNF, is needed for proper parasitemia control, very similarly to the results described for T. congolense." (PMID 32218784, 2020). "Once the concentration of TNF starts to drop, the complex dissociates and ensures the prolonged presence of the cytokine in the circulation, helping the prolonged control of parasitemia." (PMID 32218784, 2020). "This regulatory cytokine plays important role in regulating the detrimental effect of most pro-inflammatory cytokines such as TNF-α and IL-12 in a dose-dependent manner and being a significant predictor of parasitemia levels." (PMID 33281757, 2020).
parasitemia (continued). "Together, these data support that CCL3 is important for macrophage control of parasite infection and formation of an IFNγ-triggered TNF- and NO-enriched inflammatory milieu." (PMID 32194558, 2020). "Recognition of this GPI glycosyl core by IFNγ stimulated macrophages results in the induction of TNF, which is the second cytokine that is key to the optimal control of an early peak parasitemia." (PMID 32218784, 2020). "On the other hand, the reduced production of IFN-γ, IL-6, and TNF-α cytokines in C57BL/6 IL-17A knockout (IL-17A -/-) mice infected with T. cruzi Tulahuén strain produced a more severe parasitemia and mortality, than observed in wild-type mice." (PMID 33329529, 2020). "Th1 cell activation induces considerable protective immunity, which involves the initiating cytokines IFN-α and IL-12 and the effector cytokines IFN-γ and tumour necrosis factor (TNF)-α, to defend against intracellular parasitic infections." (PMID 32539714, 2020). "Mice were infected with T. cruzi and mechanical hyperalgesia, thermal hyperalgesia, blood parasitemia, survival, and TNF-α and IL-1β levels were evaluated from 2 to 28 days p.i.." (PMID 33574810, 2020). "This activation deficiency of MGL1−/− Mφ was accompanied by a remarkable downregulation of ROS and NO production, as well as by a reduction in the levels of IL-12 and TNF-α, which are important for controlling parasite infection and replication." (PMID 31906385, 2020). "NK cell-deficient mice infected with T. congolense are unable to control the levels of parasitemia due to lower levels of IFN-γ and TNF, leading to rapid onset of death due and uncontrollable parasitemia." (PMID 32595652, 2020). "Pyrogenic cytokines such as IL-1β, TNFα, IL-6 and IFNγ were significantly increased in plasma at peak parasitemia when the animals were presenting with clinical illness." (PMID 31536608, 2019). "Increased production of cytokines, particularly IFN-γ and TNF, correlated with low peak parasitemias during homologous or heterologous challenges." (PMID 30323025, 2019). "During early infection, high parasitemia resulted in activation of pro inflammatory response with high levels of TNF and IFN-γ being detected and corroborating the host attempt to eliminate the high parasite burden." (PMID 31496999, 2019). "It has long been recognized that TNF takes part in anti-Plasmodium responses that lead to intra-erythrocytic parasite killing and parasitemia reduction." (PMID 31417551, 2019). "IgM is involved in the fight against parasitic infection while cytokines, such as IL-6, IL-1β and TNF-α, had an impact on infection processes." (PMID 31882981, 2019). "At peak parasitemia, spontaneous TNF cytokine production increased significantly to 15% (IQR, 10%–18%; P = .03), indicating that CD16+ DCs were activated in vivo during a first P falciparum infection." (PMID 30239833, 2019). "On the other hand, increased TNF levels were observed in children with high-density parasitemia and when parasite clearance occurs, TNF decays." (PMID 31871954, 2019). "TNF- α appears to be crucial for parasitemia control in malaria infection (Artavanis-Tsakonaset al., 2003)." (PMID 34557294, 2019). "The TNF response appears to follow the parasitemia kinetics with increased serum levels in children with high-density parasitemia and decaying with parasite clearance." (PMID 31417551, 2019). "In vitro stimulation of TLR2/6 by T. cruzi GPI-mucins leads to the production of pro-inflammatory cytokines such as IL-12 and TNF, as well as NO, which are related to a Th1-focused immune response that is important to control parasitemia and tissue parasitism." (PMID 29868507, 2018). "We analyzed parameters related to parasitemia, plasma levels of TNF, IL-10, and CCL2, and cardiac histopathology after the administration of carvedilol for 30 days." (PMID 28377930, 2017).